RBP4 (retinol binding protein 4)
Diseases named in the same sentence as RBP4 in open-access papers (continued):
Sharing a sentence is not in itself a finding about the gene and the disease.
Obesity (continued). "With this in mind, exploring the role of RBP4, particularly among patients with obesity, could be a promising direction and could lead to better CVD prevention and management in this patient group." (PMID 32718041, 2020). "Future in-depth analyses on this area could project LSG as the most reliable treatment method for obesity and RBP4 as a trustable biomarker." (PMID 31956345, 2020). "However, in several studies, RBP4 levels were higher among individuals with obesity in comparison to control groups." (PMID 32718041, 2020). "RBP4, classified as adipokine, is proposed as the protein linking obesity and cancer." (PMID 32156052, 2020). "Retinol-binding protein 4 (RBP4) is proposed as an adipokine that links obesity and cancer." (PMID 32156052, 2020). "In the Framingham Heart Study (third generation cohort), increased levels of RBP4 and fetuin-A were observed, which was associated with the incidence of metabolic syndrome, regardless of obesity." (PMID 32718041, 2020). "In conclusion, RBP4 levels were found significant with serum UA levels in females with obesity." (PMID 31956345, 2020). "Also, an upregulation of plasma RBP4 at the 1st and 2nd trimester was modestly correlated with GDM risk, particularly among women with advanced age and obesity." (PMID 31666083, 2019). "Resistin has obesity effects, meanwhile Retinol-binding protein 4 has anti-obesity properties." (PMID 31357412, 2019). "RBP4 levels in serum are elevated in polycystic ovary syndrome (PCOS) women with obesity." (PMID 31412686, 2019). "Currently, the role of RBP4 in linking obesity and psoriasis has been given substantial attention." (PMID 31521168, 2019). "Furthermore, in psoriasis patients with obesity, the plasma levels of RBP4 are positively correlated with the PASI score and higher than those in patients with simple psoriasis." (PMID 31521168, 2019). "The findings support the hypothesis that RBP4 plays a role in the pathogenesis of the metabolic complications found in obesity." (PMID 29524177, 2018). "RBP4 is a 21 kDa secreted protein elevated in insulin resistant states such as obesity and T2DM." (PMID 30186876, 2018). "Clinical studies in adults have demonstrated associations between RBP4 levels and obesity, IR, MS and T2D, although not all studies agree." (PMID 29759068, 2018). "RBP4 is a well-established obesity factors that is overexpressed by adipose tissues." (PMID 29642915, 2018). "The concentration of RBP-4 was found to be elevated in obesity and type 2 DM, MetS and CVD." (PMID 28977161, 2017). "Thus, the targeting effect of coconut water vinegar on RBP4 and resistin clearly indicated its effectiveness in ameliorating obesity and in assisting in the reduction of serum LDL levels." (PMID 29056887, 2017). "Similar to ZIP14, GLUT4 and RBP4 expression are reduced in obesity." (PMID 28303117, 2017). "Additionally, we sought to explore the possible effect of sex hormones on the relation with obesity and RBP4." (PMID 26960804, 2016). "RBP4 could be a marker of obesity-related factors; estrogen was negatively related to RBP4 and might be one of the influential factors." (PMID 26960804, 2016). "Moreover, increased RBP4 levels are found in subjects with obesity, diabetes and cardiovascular disease." (PMID 26924713, 2016). "The association between serum Retinol Binding Protein 4 (RBP4) and obesity is still controversial." (PMID 26960804, 2016). "Therefore, when combining several factors, the group with both obesity and low estrogen level has the highest serum RBP4 levels." (PMID 26960804, 2016). "The RBP4 levels were higher in the co-presence of obesity and low estrogen, which suggested that their relationship was complicated and might influenced by estrogen and other confounding factors." (PMID 26960804, 2016). "Obesity is accompanied by increased release of free fatty acids (FFAs) and altered secretion of adipokines such as leptin, adiponectin, resistin and retinol-binding protein-4 (RBP-4) from adipocytes." (PMID 26110385, 2015).
Obesity (continued). "Hyperuricemia is likely to intensify the effect of HFCS-rich SSB intake on elevated TG levels, and being overweight/obesity may modify the action of fructose on higher circulating levels of RBP4." (PMID 24475021, 2014). "Neither component 1 nor RBP4 showed significant association with BMI of CVD subjects, indicating RBP4 as marker independent of obesity." (PMID 23119072, 2012). "We showed in this study that obesity slightly increased the Rbp4 mRNA in adipose tissue." (PMID 20307313, 2010). "RBP4 levels have been shown to increase with increasing body weight and greater distribution of central adipose tissue, which may make them a link between obesity and tumorigenesis." (PMID 41007818, 2025). "Increased white-adipose-tissue (WAT) content, which constitutes the hallmark of obesity, leads to enhanced secretion of adipokines, including leptin, resistin, interleukin 6 (IL-6), tumor necrosis factor-alpha (TNF-α), visfatin, vaspin, and retinol-binding protein 4 (RBP-4)." (PMID 38794651, 2024). "Therefore, RBP4 may be useful in identifying obesity-related asthma, differentiating it from other forms of asthma." (PMID 40980110, 2023). "Moreover, the degree of obesity is a documented, determining factor for the levels of RBP4." (PMID 36558360, 2022). "The unfavorable effects of transthyretin on T2DM could be partly attributed to indirectly elevated contents of RBP4, which appeared to be positively associated with prediabetes, T2DM, and other obesity-associated diseases in various animal and epidemiologic studies." (PMID 35889910, 2022). "Further, hepatic secretion of RBP4 does not disrupt glucose homeostasis, indicating that the modest increase in circulating levels of RBP4 in mice observed in obesity and IR might not be the cause of impaired glucose homeostasis." (PMID 36293317, 2022). "Furthermore, current studies showed that RBP4 and retinoids are strongly involved in obesity-associated dyslipidemia, but results are not fully elucidated." (PMID 34575030, 2021). "The study showed that parental obesity was associated with significantly higher serum levels of FABP4 and leptin receptor in their offspring, whereas parental DM was linked to lower adiponectin but higher retinol binding protein 4 concentrations in the offspring." (PMID 30818771, 2019). "Therefore, RBP4 could be a molecular bridge between obesity and cancers and a potential target for treating obese cancer patients." (PMID 29642915, 2018). "We here investigated whether RBP4 is a tumorgenic factor that connects obesity and ovarian cancer." (PMID 29642915, 2018). "Thus, RBP4 could be a molecular bridge between obesity and cancers and a potential target for treating obese cancer patients." (PMID 29642915, 2018). "Therefore, the relationship of RBP4 and obesity is still controversial in adult." (PMID 26960804, 2016). "Transtyretin is bound to RBP4 in plasma and an elevation in RBP4 is thought to contribute to the development of IR associated with obesity and T2DM A decrease in transthyretin could result in increased free RBP4 levels contributing to IR in obese subjects, with weight loss improving this impairment." (PMID 24949022, 2014). "Therefore, specific small molecule inhibitors such as KMU-3 identified in this study are useful leads for future drug development efforts for prevention and/or treatment of obesity and/or obesity-related disease in which overexpression of leptin, RBP4, and/or RANTES plays pathological roles." (PMID 25285517, 2014). "The striking downregulation of retinol-binding protein 4 (RBP4) mRNA to <10% of Uremic group levels in both PD and EPS groups has been associated with lean body mass and with ovarian cancer, but impaired glucose tolerance and obesity were associated with elevated serum RBP4." (PMID 23418565, 2013). "Furthermore, high plasma RBP4 has been associated with systemic inflammation in chronic kidney disease in the absence of obesity and diabetes." (PMID 23799122, 2013).
Obesity (continued). "Furthermore, calorie restriction and obesity have drastic opposing effects on pro- and anti-inflammatory genes as well as genes involved in adipose tissue energy metabolism such as Lpin2, Kcnj11 and Rbp4." (PMID 20307313, 2010). "Elevated IL-6 expression was associated with older age and obesity-related parameters, while RBP4 overexpression correlated with tumor size, lymph node metastasis, advanced TNM stage, and markers of obesity, such as increased BMI and waist circumference." (PMID 41007818, 2025). "The regulation of the insulin pathway by RBP4 or AGP, the involvement of A1M in obesity, endoplasmic reticulum stress, and the role of LCN2 and AGP in modulating food intake behavior are only some of the noteworthy features." (PMID 38673873, 2024). "The results of the correlation analysis are the first in the literature and show the relationship between plasma irisin, RBP-4, and adiponectin in OSAS patients with obesity and type 2 DM." (PMID 37892122, 2023). "Retinol-binding protein 4 (RBP4) has been considered to be related to metabolic related diseases, such as hyperuricemia, obesity, and diabetes mellitus." (PMID 36670387, 2023). "In contrast, SM (OH)s, SM (2OH)s, and GSLs exhibited favorable correlations with obesity (rs = −0.07 to −0.19), triglycerides/HDL-cholesterol (rs = −0.08 to −0.20), CRP (rs = −0.08 to −0.14), adiponectin (rs = 0.06 to 0.15), and RBP4 (rs = −0.06 to −0.15)." (PMID 34208976, 2021). "Special attention was given to the effect of C3G on retinol binding protein 4 (RBP4), which is elevated in rodent and human obesity and type-2 diabetes." (PMID 33233708, 2020). "Hence, we suggest that RBP4 may play a role in thyroid dysfunction in obesity." (PMID 31956345, 2020). "A more favorable adipokine profile, characterized by decreased osteonectin, leptin, and RBP-4 and increased adiponectin levels was shown in MHO children with respect to metabolically unhealthy children suffering from obesity." (PMID 33192583, 2020). "As obesity progresses, proinflammatory adipokines, including leptin, TNF, resistin, IL-6, RBP4, lipocalin-2, and ANGPTL-2, are preferentially synthesized and cause chronic inflammation." (PMID 33133214, 2020). "Other adipokines, such as PRGN (also known as granulin/epithelin precursor), nesfatin-1 (nesfatin), visfatin/PBEF/NAMPT, apelin, RBP-4, and PAI-1 have been described as signal molecules involved in obesity and metabolic syndrome." (PMID 33192583, 2020). "RBP-4 positively correlated with GLUT-4 expression in adipose tissue, independently of any obesity variable." (PMID 33133591, 2020). "In this non-systematic review, we have characterized one of the novel adipokines—retinol-binding protein 4 (RBP4), with a particular emphasis on its role in obesity and CVD development." (PMID 32718041, 2020). "The secretion of these proinflammatory cytokines and chemokines, as well as the secretion of other adipokines like retinol binding protein 4 (RBP4) 141, 142, is now well admitted to contribute to the onset of the physiological alterations accompanying obesity." (PMID 31423716, 2019). "Retinol binding protein 4 (RBP4) is an adipokine that drives the development of hyperinsulinemia and type II diabetes in obesity patients and animals." (PMID 29642915, 2018). "Obesity also affects the production of adiponectin (ADIPOQ), leptin and retinol binding protein 4 (RBP4)." (PMID 25938677, 2015). "The study reported that RBP4 was elevated in insulin-resistant mice with adipose tissue-specific GLUT4 knockout and humans with obesity and type 2 diabetes mellitus." (PMID 24160775, 2013). "This suggests that elevated RBP4 and fetuin-A serum levels do not represent an independent mechanism linking adipose tissue dysfunction to impaired glucose metabolism, whereas chemerin may be closely reflect causation in obesity-related glucose intolerance." (PMID 21085476, 2010).
Obesity (continued). "Research indicates that CLU expression and circulating levels increase with obesity and visceral adiposity, correlating with chronic low-grade inflammation, high-sensitivity C-reactive protein (hs-CRP), retinol-binding protein-4, and other proinflammatory markers." (PMID 41515662, 2026). "Won and colleagues indicated that circulating CLU levels are significantly correlated with adiposity and inflammatory markers, including BMI, waist circumference, hs-CRP, and RBP-4, and established that CLU is indicative of obesity-related chronic inflammation." (PMID 41515662, 2026). "However, some proteins were primarily affected by other factors: SHBG by age and obesity; PRG4 by obesity; and IGF1 and RBP4 by age." (PMID 39972214, 2025). "RBP4 is recognized as a negative acute inflammatory reactant and as a novel adipokine, whose levels increase in insulin-resistant conditions, such as obesity, metabolic syndrome, type 2 diabetes mellitus, as well as cardiovascular diseases." (PMID 41227378, 2025). "Adipocyte-derived proteins including leptin, adiponectin, visfatin, and omentin possess antidiabetic activity and some proteins are pro-hyperglycemic such as resistin, inflammatory cytokines, and retinol-binding protein 4 (RBP4), which are involved in the pathophysiology of obesity and diabetes." (PMID 40094833, 2025). "Besides RBP4, lipocalin-2 (LCN-2) is another protein that belongs to the lipocalin family which also plays a significant role in obesity-related diseases." (PMID 39139157, 2024). "For RBP4, this marker is thought to be increased in overweight and obesity and is an adipokine with properties independent of retinol transport protein." (PMID 38686175, 2023). "Subsequently, we investigated the patterns of the mRNA expression of adipokine in the gingiva of the four groups and surprisingly found the upregulation of RBP4 and asprosin levels in the periodontitis group with/without the presence of obesity." (PMID 38069063, 2023). "The meta-analysis revealed that the circulating levels of RBP4 in patients with periodontitis and obesity were not significantly different from those in periodontally healthy patients." (PMID 38132460, 2023). "A study on asthma in adolescents investigated retinol-binding protein (RBP4) and plasminogen activator inhibitor (PAI-1) and found that RBP4 was useful in predicting non-allergic asthma in adolescents with obesity." (PMID 40980110, 2023). "Irisin and adiponectin levels were significantly lower and RBP-4 levels were significantly higher in patients with obesity compared to those without obesity." (PMID 37892122, 2023). "To date, the relationship between RBP4 and periodontitis in patients with or without obesity still remains controversial." (PMID 38132460, 2023). "The induction and progression of RBP-4-induced retinal neurodegeneration appears to be independent of retinal vascular pathology, obesity, dyslipidemia, and hyperglycemia." (PMID 37883447, 2023). "Western blot analysis showed that the RBP4 level was dramatically enhanced in the gingiva of periodontitis in the presence and absence of obesity." (PMID 38069063, 2023). "There is increasing evidence that RBP4 induces IR and is closely related to T2DM, obesity, and MBS." (PMID 36203073, 2022). "In addition to its hepatic secretion, RBP4 is secreted by SAT and VAT, with a more pronounced production in the latter in states of obesity and diabetes." (PMID 35406450, 2022). "Additionally, RBP4 expression in adipose tissues is regulated by 17-estradiol, and the levels of RBP4 in serum are elevated in women with PCOS and obesity." (PMID 34068244, 2021). "Previous studies had shown that RBP4 was elevated both circulating and in adipose tissue of patients with obesity with or without diabetes, which was tightly associated with IR in most, if not all, studies." (PMID 34177800, 2021).
Obesity (continued). "Very few studies have explored the role of RBP4 in systemicinflammation, more so in the absence of obesity and related metabolic alterations." (PMID 33222545, 2021). "RBP4 and FABP4 could be considered as detrimental to metabolism because they exhibit high circulating levels and adipose tissue gene expression with obesity related disorders." (PMID 34638803, 2021). "Since RBP4 may be correlated with conditions related to Type 2 diabetes mellitus (T2DM), obesity, or CVD, the RBP4 gene may constitute the gene carrying obesity-related implications." (PMID 32718041, 2020). "In this similar pattern, our study results show RBP4 levels were significantly and positively associated with TCH and TG in females with obesity but not in males." (PMID 31956345, 2020). "Omega-3 supplementation decreased RBP4 levels among adolescents with obesity; however, the effect was not statistically significant when compared to lifestyle intervention alone." (PMID 32718041, 2020). "In our study, we have demonstrated that RBP4 concentration was significantly elevated in the plasma of patients with obesity compared with non-obese group, which was consistent with previous investigation." (PMID 29335416, 2018). "A statistically significant synergistic effect of PCOS and obesity was found for RBP4, and although not statistically significant for GLUT4, the lean controls appeared to be substantially different from both PCOS groups with regards to GLUT4 expression." (PMID 28303117, 2017). "And the same link between circulating RBP4 levels and obesity indices was not founded in obese women, which implied that there are other mechanisms for regulating RBP4 levels." (PMID 26960804, 2016). "This suggests that a subgroup of individuals with obesity and T2D are characterized by additional alterations in lipid metabolism, which may be reflected or mediated by adipokines including SFRP5, RBP4, CTRP3 and 5, omentin and adiponectin." (PMID 24968098, 2014). "In present study, we found that serum RBP4 levels were significantly increased in the hypertensive subjects but do not contribute to IR after excluding the confounders of obesity." (PMID 24932224, 2014). "This may suggest that under conditions of T2D and obesity, adiponectin, omentin, CTRP3 and 5, RBP4 and SFRP5 reflect additional alterations in lipid metabolism." (PMID 24968098, 2014). "Furthermore, patients with obesity (BMI ≥ 30 kg/m2) demonstrated significantly higher RBP4 expression compared to non-obese patients (p = 0.0264)." (PMID 41007818, 2025). "In contrast, the adipogenesis genes COL12A1, FBN1 and RBP4, as well as the genes CASP6 and DPT that involved in inflammation or immune response, were downregulated in obese pigs but upregulated in obese human, consistent with previous reports showing their upregulation in obesity." (PMID 40658709, 2025). "Importantly, VAT mass reduction—accompanied by improved insulin sensitivity—is associated with an approximately 25% decrease in circulating RBP4 in non-diabetic individuals with obesity." (PMID 41303567, 2025). "Unlike the results in RBP4 and asprosin, obesity could independently or collectively act as an interfering factor in significantly upregulating the expression of leptin, nampt/visfatin and resistin." (PMID 38069063, 2023). "Therefore, RBP4 may act as another promising candidate for ATM-based HGP modulation, particularly in obesity-related glucose dysregulation." (PMID 36091076, 2022). "Most of ceramides, dhCers, and SMs showed unfavorable correlations with obesity (rs = 0.06 to 0.15), triglycerides/HDL-cholesterol (rs = 0.06 to 0.28), CRP (rs = 0.06 to 0.17), IL-6 (rs = 0.07 to 0.13), adiponectin (rs = −0.06 to −0.14), and RBP4 (rs = 0.06 to 0.24)." (PMID 34208976, 2021). "In healthy individuals, normal serum RBP4 ranges from 10 to 50 μg/mL (without vitamin A deficiency), but among individuals with Type 2 diabetes, CVD or obesity, it may reach up to 150 μg/mL." (PMID 32718041, 2020).